RET (ret proto-oncogene)
Diseases named in the same sentence as RET in open-access papers (continued):
Sharing a sentence is not in itself a finding about the gene and the disease.
osteosarcoma (17 papers, 2019 to 2025). A usually aggressive malignant bone-forming mesenchymal neoplasm, predominantly affecting adolescents and young adults. "It has also been confirmed that the overexpression of RET is associated with chemotherapeutic resistance induced by cisplatin and bortezomib, and with the increase of stem cell-like properties of osteosarcoma." (PMID 32984034, 2020). "NGF–TrkA shows highest expression; BDNF–TrkB and GDNF–GFRα/RET are variable, whereas NT−3/TrkC is low in osteosarcoma but prominent in other bone sarcomas, hence our emphasis." (PMID 41142827, 2025). "By comparing the targets of mTKIs, studies indicate that VEGFRs and RET are the key targets for osteosarcoma treatment." (PMID 40344484, 2025). "Ectopic expression of MALAT1 increased proliferation, migratory and invasive ability in osteosarcoma cells and promoted tumor growth in mice via sponging miR-129-5p and regulating the RET-Akt pathway." (PMID 35252166, 2022). "All multi-target TKIs (apatinib, cabozantinib, lenvatinib, regorafenib, and sorafenib) with high efficiency in osteosarcoma are inhibitors of RET." (PMID 32984034, 2020). "Using phosphoproteomic screening, RET was first identified in vitro as a receptor that can promote behavior of metastatic osteosarcoma cells and is thought to be a potential therapeutic target for osteosarcoma." (PMID 32984034, 2020). "Instead of transactivating HSPA5 in OS cells 7, 8, ATF4 negatively regulates GRP78 transcription in BTZ-resistant OS cells, thus reinforcing the therapeutic effect of BTZ by the dual targeting of GRP78 and RET in the context of osteosarcoma chemoresistance." (PMID 31534554, 2019). "Our results showed a previously undescribed drug resistance mechanism in which GDNF-mediated RET phosphorylation at Y1062 promotes osteosarcoma progression by stimulating downstream AKT and ERK pathways." (PMID 31534554, 2019). "TKIs such as apatinib, lenvatinib and sorafenib, which target VEGFRs and RET, are viable therapeutic alternatives for osteosarcoma and may affect patient prognosis." (PMID 41479782, 2025). "There are many clinical trials on the role of RET in osteosarcoma." (PMID 32984034, 2020). "We compared the targets of these TKIs and found that VEGFRs and RET may be the key RTKs for the treatment of osteosarcoma." (PMID 32984034, 2020). "The role of RET in osteosarcoma has been far less studied than in other malignancies." (PMID 32984034, 2020). "More importantly, studies on the role and mechanism of RET in the treatment of osteosarcoma by multi-target TKIs may yield unexpected results." (PMID 32100146, 2020). "In conclusion, RET is an important and potentially critical target for osteosarcoma treatment, and it may be equally important as VEGFRs." (PMID 32984034, 2020). "As BTZ is a well-characterized proteasome inhibitor 7, we hypothesized that the RET protein is preserved by long-term BTZ treatment in osteosarcoma via the development of a unique resistance mechanism." (PMID 31534554, 2019). "Key RTKs for osteosarcoma treatment may include VEGFRs and RET." (PMID 32984034, 2020). "The key targets for osteosarcoma treatment may include VEGFRs and RET." (PMID 32984034, 2020). "This study suggested that MALAT1 enhanced stem cell-like features via promotion of RET expression via targeting miR-129-5p and subsequently activating the PI3K-Akt pathway in osteosarcoma." (PMID 35252166, 2022). "For example, SRC kinase, which plays a key role in the development of osteosarcoma, can be activated, respectively by VEGFRs, KIT, RET, PDGFRs, IGF-1R, and AXL." (PMID 32984034, 2020). "In osteosarcomas, MALAT1 increased stem cell-like properties by regulating the expression of RET via sponging miR-129-5p." (PMID 32377169, 2020). "For example, MALAT1 increases stem cell-like properties by up-regulating RET in sponge mir-129-5p, thus activating the PI3K-Akt signaling pathway and providing potential therapeutic targets for osteosarcoma treatment." (PMID 32883200, 2020).
osteosarcoma (continued). "Because PD-1/PD-L1 monotherapy yields <10% responses in relapsed osteosarcoma, interrupting this circuit via TRK/RET inhibition or macrophage re-education may unlock checkpoint synergy." (PMID 41142827, 2025). "The absence of RET upregulates ATF4, which accelerates the turnover of RET proteasomes by over-recruitment of its trans-activated E3 ligase CPL-C, thereby enhancing the chemotherapy effect of BTZ and preventing BTZ resistance in osteosarcoma cells." (PMID 36551309, 2022). "ATF4 devastates RET by inhibiting nonclassical GRP78 to increase osteosarcoma chemosensitivity to bortezomib." (PMID 36303551, 2022). "Further, the three multi-target TKIs (axitinib, cediranib, and imatinib) with low efficiency in osteosarcoma do not inhibit RET." (PMID 32984034, 2020). "These three TKIs share a distinctive sensitivity for VEGFR2 and RET, suggesting that RET, like VEGFR2, may be an important specific target in the treatment of osteosarcoma." (PMID 32100146, 2020). "Interestingly, pediatric recurrent osteosarcoma patients can receive innovative targeted treatments, in the context of basket trials; selpercatinib (NCT04320888) is tested in patients carrying RET gene alterations, reported to be present in 4% of osteosarcomas." (PMID 33917001, 2021). "The role of RET in osteosarcoma has not been studied in detail and warrants further study." (PMID 32984034, 2020). "Unlike cisplatin chemoresistance in osteosarcoma, where GFRα1 regulates autophagy independent of the proto-oncogene RET kinase 44, RET was recognized as a functional driver of BTZ resistance in osteogenic sarcoma, suggesting RET as a target for the treatment of advanced osteosarcoma." (PMID 31534554, 2019).
follicular thyroid carcinoma (16 papers, 2007 to 2025). "RAS mutations appeared mainly in the follicular variant PTC and follicular thyroid carcinoma, while RET and NTRK fusions remained common FAs, consistent with previous literature." (PMID 40895628, 2025). "In our recent study, we found no statistical significance in the prevalence of BRAF V600E, RET/PTC rearrangements or RAS mutations in papillary and follicular thyroid carcinomas from an iodine-rich country (Japan) and an iodine-deficient country (Vietnam)." (PMID 27793009, 2017). "Rearrangement of the RET and PAX8-PPARγ1 gene is found frequently in papillary and follicular carcinomas, respectively, but not in anaplastic carcinomas." (PMID 17453004, 2007).
gastrointestinal stromal tumor (15 papers, 2011 to 2026). "Sunitinib targets VEGFR-1/2/3, PDGFR, c-Kit receptor, fms-like tyrosine kinase-3 receptor (FLT-3), and receptor encoded by the ret proto-oncogene (Ret) and is approved for treatment drug-resistant gastrointestinal stromal tumours (GIST) and RCC." (PMID 38590656, 2024). "This has been the case for agents targeting c-kit in gastrointestinal stromal tumors (GIST) or RET in medullary thyroid cancer." (PMID 26446908, 2015). "Sunitinib is an orally bioavailable multityrosine kinase inhibitor that blocks VEGFR1-3, Flt-3, PDGFR-α, PDGFR-β, c-Kit, CSF-1R, and RET with proven antitumor activity in renal cell carcinoma and imatinib-resistant or -intolerant gastrointestinal stromal tumor (GIST)." (PMID 21961001, 2012). "Sunitinib (Sutent®) is a multikinase inhibitor of VEGFR 1–3, RET and PDGFRα/β, currently approved for the treatment of RCC, imatinib-resistant gastrointestinal stromal tumors (GIST) and pancreatic neuroendocrine tumors (pNET)." (PMID 22072937, 2011). "Sunitinib (SU011248), a small molecule inhibitor of class III and class IV receptor tyrosine kinases, including VEGFR1-3, PDGFR-α/β, c-Kit, Flt3, and RET, is currently approved for the treatment of renal cell carcinoma (RCC) and imatinib-refractory gastrointestinal stromal tumors (GIST)." (PMID 28384190, 2017). "Inhibition of RET and KIT supports its therapeutic role in thyroid cancers and gastrointestinal stromal tumors (GIST), particularly in the context of resistance to earlier-generation TKIs." (PMID 41517566, 2026). "Sunitinib (Sutent) is a multi-kinase inhibitor of VEGFR 1-3, RET and PDGFR, approved for treatment of RCC, imatinib-resistant gastrointestinal stromal tumors (GIST) and pancreatic neuroendocrine tumors (pNET)." (PMID 22830012, 2012). "Sunitinib, already approved for the treatment of imatinib-resistant gastrointestinal stromal tumors (GIST), advanced renal carcinoma and advanced pancreatic neuroendocrine tumors, is the subject of a phase II study in certain types of LAD tumors, including those harbouring a RET fusion." (PMID 27429741, 2016).
glioblastoma (15 papers, 2014 to 2024). The most malignant astrocytic tumor (WHO grade IV). "Among the confirmed proteins, RET, an oncogene, is known to play a role in the development of the central and peripheral nervous system, and EGFR is one of the most frequently mutated genes in glioblastoma." (PMID 36834486, 2023). "In addition, a documented response to selpercatinib was observed in a patient with RET-amplified glioblastoma." (PMID 37627175, 2023). "In addition, MAZ promoted tumor angiogenesis in human glioblastoma through transcriptional regulation of VEGF and controlled liposarcoma cell proliferation and apoptosis through directly regulating GNDF in RET signaling with synergy interaction of SPN1." (PMID 27861158, 2016).
Hashimoto thyroiditis (15 papers, 2006 to 2025). An autoimmune disorder caused by the production of autoantibodies against thyroid tissue. "RET and CCDC6 fusions were associated with type of thyroidectomy, RAI therapy, smaller tumor size, and history of Hashimoto’s disease." (PMID 39409115, 2024). "The aim of study was an assessment of RET/PTC1 and RET/PTC3 rearrangements in patients with Hashimoto's thyroiditis." (PMID 21219595, 2011). "Our results indicate that RET/PTC1 and RET/PTC3 rearrangements in Hashimoto's thyroiditis, if any, are rather rare events and further investigations should be conducted in order to determine molecular changes, connecting Hashimoto's thyroiditis with PTC." (PMID 21219595, 2011). "The prevalence of RET/PTC rearrangements in Hashimoto's thyroiditis remains a subject of controversy." (PMID 21219595, 2011). "For instance, RET and CCDC6 fusions clustered with variables such as type of thyroidectomy, the need for RAI therapy, smaller tumor size, Hashimoto’s disease, and hypothyroidism." (PMID 39409115, 2024). "Recently, RET/PTC rearrangements have been shown not only in PTC but also in Hürthle thyroid adenomas and carcinomas and also in Hashimoto's thyroiditis (HT)." (PMID 21219595, 2011). "Recently, RET/PTC rearrangements have been shown not only in PTC but also in benign thyroid lesions, including Hashimoto's thyroiditis (HT)." (PMID 21219595, 2011). "At the molecular level, upregulation of the RET/RAS/BRAF/ERK/MAPK pathway, which has the capability to induce both a proinflammatory and a protumourigenic thyroid programme, is a possible mechanism linking chronic thyroiditis with carcinogenesis." (PMID 28572821, 2017). "In summary, the results of our study indicate that RET/PTC1 and RET/PTC3 rearrangements in Hashimoto's thyroiditis, if any, are rather rare events and further investigations seem to be necessary to determine molecular changes associating Hashimoto's thyroiditis with PTC." (PMID 21219595, 2011). "Definitive evidence that Hashimoto's thyroiditis is caused or exacerbated by RET/PTC3 is not yet available, although sufficient evidence exists to support a direct role for activated RET kinase in inducing the mediators of inflammation in vitro and in vivo." (PMID 18304343, 2008). "In addition to papillary thyroid carcinoma (PTC), recent studies revealed incidence of RET/PTC rearrangement in other tumors, like Hürthle cell carcinoma (HCC) and even in non-carcinomatous disorders like Hashimoto's thyroiditis." (PMID 31754366, 2019). "Clonal RET /PTC rearrangements occur in about 20% of PTC and are specific for this tumor Non-clonal RET /PTC rearrangements have been found not only in PTC but also in 10–45% of thyroid adenomas and other non-neoplastic thyroid lesions and Hashimoto’s thyroiditis." (PMID 24868250, 2013).
prostate carcinoma (15 papers, 2006 to 2025). A carcinoma that arises from epithelial cells of the prostate gland. "Taken together, these findings suggest that aberrant RET activity may be actionable in prostate cancers, including those associated with neuroendocrine malignancies." (PMID 35957881, 2022). "GDNF and GFR α 1 are secreted by the increased nerves in the peritumoral stroma of prostate cancer to create a perineural niche where RET signaling can occur." (PMID 35582425, 2022). "It is important to note, however, that while RET overexpression is frequently found in prostate cancers, RET alterations are found in 1-2% of prostate cancer cases." (PMID 35957881, 2022). "Overexpression of wild-type RET in prostate cancer was first demonstrated by Robinson and colleagues using a prostate cancer xenograft model." (PMID 35957881, 2022). "Together, these data indicate that GDNF stimulation is associated with reduced RB activity and enhanced E2F1 and AR target gene expression in a subset of prostate carcinoma that are receptive to GDNF signaling by virtue of RET and/or GFRA1 receptor expression." (PMID 25575823, 2015). "RET is a transmembrane protein tyrosine kinase characterized by proto-oncogenic properties, and it has been identified as a potential promoter of the invasive capabilities of prostate cancer through the activation of p70S6 kinase." (PMID 39771106, 2024). "Similarly, the proliferation and survival of pancreatic and prostate cancer cell lines that often express GFRɑ1 and RET can be promoted by GDNF." (PMID 32993133, 2020). "However, the co-dependency with RET revealed the association of ZBTB7A in SCN HI cells, suggesting that co-dependency analysis with RET, a possible emerging NEPC target, can distinguish the roles of ZBTB7A in different prostate cancer subtypes." (PMID 37065756, 2023). "However, the increase in RET activity within prostate cancers may also be attributed to increased secretion of GDNF by prostatic stromal cells or GFRα1 by peripheral nerves within the prostate, ultimately promoting perineural invasion of prostate cancers." (PMID 35957881, 2022). "BRAF gain-of-function alteration, RET fusion, and NTRK fusion are rare alterations detected by CGP testing in patients with prostate cancer." (PMID 41158701, 2025). "Cabozantinib is an orally bioavailable small molecule inhibitor of c-Met, RET, ROS1, Alk, VEGFR2, and TRK receptors with approved uses for the treatment of metastatic medullary thyroid cancer, prostate cancer and advanced renal cell carcinoma." (PMID 30885237, 2019). "We analyzed publicly available data at The Human Protein Atlas data repository to determine the expression patterns of RET and GFRA-family members in clinical prostate cancer." (PMID 25575823, 2015). "The majority of prostate cancers expressed GFRA1 (82%) and all tumors showed RET expression, indicating that a majority of localized prostate cancers are potentially sensitive to GDNF." (PMID 25575823, 2015). "There have been no case reports of successful treatment of prostate cancer with RET fusion and NTRK fusion to date." (PMID 41158701, 2025). "Furthermore, we plan to develop a similar approach toward other gene fusions, such as ROS1, RET, and NTRK in NSCLC, but also gene fusions identified in other solid cancers, such as TMPRSS2-ERG in prostate cancer, EVT6-NTRK3 in secretory breast carcinoma etc." (PMID 37016288, 2023). "Fibroblast GDNF exerted paracrine effects toward prostate cancer cells resulting in enhanced tumor cell proliferation and invasion, and these effects were concordant with the expression of known GDNF receptors GFRA1 and RET." (PMID 25575823, 2015). "Furthermore, GDNF stimulation increased the proliferation rate of prostate cancer cells and activated the signal pathway through GFRα1/SRC pathway, which was related to the expression level of GFRα1, but not related to RET." (PMID 35582425, 2022).
squamous cell carcinoma (15 papers, 2015 to 2025). A carcinoma arising from squamous epithelial cells. "In patients with squamous cell carcinoma, approximately 30% of tests for EGFR, ALK, and RET mutations were positive, which confirms the importance of testing at least a preselected subgroup of patients." (PMID 39518907, 2024). "RET rearrangements have previously been reported in squamous cell carcinoma, lung neuroendocrine tumor and adenosquamous tumor; however, the majority occur in adenocarcinomas." (PMID 25881079, 2015). "Histological analysis revealed that B[a]P 10 μM and RET 40 μM exposure predominantly induced papillomatous epithelial tumours, whereas DMBA 10 μM exposure resulted in invasive squamous cell carcinomas." (PMID 40211435, 2025). "Patients with RET fusions in this study were younger (p = 0.004), more likely to be diagnosed with non-squamous cell carcinoma (p < 0.001), nonsmokers (p < 0.0001) and had better performance status (p = 0.01)." (PMID 33402119, 2021).
leukemia (14 papers, 2010 to 2024). A malignant (clonal) hematologic disorder, involving hematopoietic stem cells and characterized by the presence of primitive or atypical myeloid or lymphoid cells in the bone marrow and the blood. "Further, downstream RET‐mTORC1 signalling is found to promote AML cell growth through the suppression of autophagy and stabilization of leukaemia‐genic drivers, indicating the potential of RET as a therapeutic target in subgroups of AML patients." (PMID 32573073, 2020). "Overexpression of human FST317 and FST344 isoforms enhanced clonogenicity and leukemia engraftment in xenotransplantation model via RET,IL2RA, and CCL5 upregulation." (PMID 32134197, 2020). "Previous studies found differential expression of RET in acute myeloid leukemia, a distinct but related leukemia." (PMID 25057111, 2014). "RET is differentially expressed in human AML, with highest levels in leukemia with monocytic differentiation, which nicely fits to the acute myelomonocytic leukemia of our GEMM." (PMID 34903841, 2022). "FST upregulated expression of RET, IL2RA, and CCL5 that collectively potentiated MAPK signaling and promoted leukemia growth in vitro and in vivo." (PMID 32134197, 2020). "We measured the expression of genes coding RTKs: FLT3, KIT exclusively in leukemia cell lines, PDGFRa, AXL in NB, NTRK1, FGFR3, INSR, ROR2, and RET in both NB and leukemia cells by qRT-PCR, which were top-scoring RTK-coding genes among leukemia and NB cell lines." (PMID 34944663, 2021). "Thus, in contrast to E2a:PBX leukaemia, Eμ-RET pre-B cell ALL did not relapse following CD19 CAR via lineage switch suggesting that the occurrence of this resistance mechanism may depend on the genetic driver." (PMID 27460500, 2016).
renal cell carcinoma (14 papers, 2011 to 2025). "Sunitinib, targeting VEGFR1-3, PDGFR-α/β, KIT, FLT-3, colony-stimulating factor receptor Type 1 (CSF-1R), RET, for gastrointestinal stromal and pancreatic cancers and renal cell carcinoma." (PMID 34956857, 2021). "Likewise, the RET-targeting TKI, Sunitinib, mediates its renal cell carcinoma anti-tumor effect via tumor-associated endothelial cells and not tumor cells." (PMID 30701022, 2018). "Among the most interesting cases are the rare germline CNVs affecting RET in GBMs, ERBB2 in renal cell carcinomas, and DCC in ovarian cancers." (PMID 25644941, 2015). "Interestingly, TMEM127 mutations have also been identified as drivers in other cancers, notably renal cell carcinoma, where RET is not highly expressed." (PMID 38687678, 2024).